MMP11 (matrix metallopeptidase 11)
Diseases named in the same sentence as MMP11 in open-access papers (continued):
Sharing a sentence is not in itself a finding about the gene and the disease.
colon carcinoma (16 papers, 2011 to 2026). "We found that the MMP-11 SNP rs738792 “TC + CC” genotype was significantly associated with perineural invasion in colon cancer patients after controlling for clinical parameters [OR (95% CI) = 1.783 (1.074–2.960); p = 0.025]." (PMID 35885589, 2022). "Distinct colon cancer-associated fibroblast (CAF) subtypes were found to express different MMP combinations, including MMP1/3-expressing and MMP11-expressing CAFs." (PMID 42079046, 2026). "MMP11-directed vaccine induced cell-mediated and antibody immune response and exerted significant antitumor protection in mice with colon cancer in prophylactic and therapeutic settings." (PMID 40122809, 2025). "Another example of a condition where researchers are evaluating the relationship between serum MMP-11 levels and patient prognosis is colon cancer." (PMID 38203373, 2023). "This proof of principle study shows the potential of in situ sequencing revealing novel potential predictive biomarkers in colon cancer stage II, namely MMP11, FGFR2 and OTOP2, relevant for relapse of disease." (PMID 37543577, 2023). "In colorectal cancer, it was suggested that MMP-11 is highly expressed in colonic carcinoma, and the elevated serum levels and mRNA expression of MMP-11 were correlated with poor prognosis in colon cancer patients." (PMID 35885589, 2022). "Eight significantly over‐expression genes in tumour tissues (BGN, THBS2, SPARC, CDH11, MFAP2, MMP11, SPP1 and THY1) were defined as significantly signature genes that implicated in colon cancer metastasis progress." (PMID 36377223, 2022). "They found that the serum levels of MMP11 were substantially higher in colon cancer patients than in healthy controls and was an independent predictor of the OS and DFS of colon cancer." (PMID 34804973, 2021). "measured the serum levels of MMP11 in 92 colon cancer patients and 92 healthy individuals using ELISA." (PMID 34804973, 2021). "Clinical trials have demonstrated that a high level of MMP-11 expression is correlated with a lower survival rate among patients with breast, non-small cell lung cancer and colon cancer." (PMID 21513571, 2011). "Interestingly, patients with other types of cancer exhibit elevated levels of MMP-11 compared to healthy patients—such results have been reported in patients with colon cancer and uterine corpus endometrial carcinoma." (PMID 41007705, 2025). "Sp1 also interacts with Smad and promotes MMP11 expression in colon cancer cells." (PMID 29215776, 2018). "Importantly, FGFR2 and MMP11 are druggable targets in other cancer entities and could become novel predictive biomarkers in stage II colon cancer." (PMID 37543577, 2023). "We were able to identify FGFR2, MMP11 and OTOP2 as upregulated genes in tumour compartments of relapsed patients diagnosed with stage II colon cancer." (PMID 37543577, 2023). "We thereby identified FGFR2, MMP11 and OTOP2 as three differentially expressed genes in the neoplastic tissue predicting tumour recurrence in stage II colon cancer." (PMID 37543577, 2023). "This is especially true for the three identified genes, MMP11, FGFR2 and OTOP2, which need validation in an equivalent stage II colon cancer cohort with conventional immunostaining procedures." (PMID 37543577, 2023). "The levels of MMPs including MMP-2, MMP-9, MMP-11, and MMP-19 are elevated in the colon cancer patients as compared to normal individuals." (PMID 34096454, 2021). "To check this, we transfected pre-miR-21 in colon cancer LS174 cells and found a similar increase in MMP-2, MMP-9 and MMP-11, as was seen when cells were exposed to cancer cell-derived exosomes." (PMID 32427870, 2020). "Cancer-by-cancer, lung squamous (LUSC) has two MMPs with sensitivities over 95% (MMP11 and MMP12), colon cancer (COAD) has three over 94% (MMP11, MMP28, and MMP7), and esophageal cancer (ESCA) has two over 94% (MMP11 and MMP12)." (PMID 31200666, 2019).
colon carcinoma (continued). "Three differentially expressed genes (FGFR2, MMP11 and OTOP2) in the neoplastic tissue compartments of relapsed patients in comparison to non-relapsed patients were identified predicting recurrence in stage II colon cancer." (PMID 37543577, 2023). "Therefore, we next determined levels of endogenous miR-21 and ECM mediators in colon cancer cell line LS174 by RT-qPCR, and found a positive correlation between miR-21 and ECM mediators MMP-2, MMP-9, and MMP-11, but not between miR-21 and ECM inhibitor TIMP-2." (PMID 32427870, 2020).
colorectal cancer (16 papers, 2014 to 2025). A primary or metastatic malignant neoplasm that affects the colon or rectum. "In one of the few studies involved colorectal cancer patients, these patients also had higher levels of MMP-11 (median: 38.98 mg/mL) compared to healthy subjects (5.86 ng/mL)." (PMID 38892452, 2024). "MMP-11 belongs to the zinc-dependent endopeptidases family, and is expressed in colorectal cancer cells and macrophages in tumor tissues." (PMID 38627864, 2024). "The experimental results confirmed that the concentration of MMP-9 and MMP-11 was higher in patients with colorectal cancer compared to the concentration level in healthy patients." (PMID 38203373, 2023). "In the results, the authors showed that serum MMP-11 levels were higher in patients with colorectal cancer compared to healthy control patients." (PMID 38203373, 2023). "We observed that MMP-11 expression was prone to be upregulated in colorectal carcinoma tissue compared with normal tissues." (PMID 35885589, 2022). "MMP11 upregulation has also been related to lymph node metastasis in non-small cell lung cancer and colorectal cancer." (PMID 33648461, 2021). "Our study has demonstrated that CD147 and MMP-11 are overexpressed in colorectal cancer, and there’s a positive correlation and co-localization between these two proteins." (PMID 26507719, 2015). "This study aimed to investigate the expression of CD147 and MMP-11 in human colorectal cancer (CRC) and to evaluate their clinical significance." (PMID 26507719, 2015). "Thus, MMP11 plays an important role in colorectal cancer development, and its mechanism in CRC needs to be further explored in the future." (PMID 39239548, 2024). "Furthermore, analyses of The Cancer Genome Atlas (TCGA) revealed that MMP-11 levels were upregulated in colorectal carcinoma tissue compared with normal tissues and were correlated with advanced stage, larger tumor sizes, and lymph node metastasis." (PMID 35885589, 2022). "Another let-7 family member, let-7c, targets MMP11 to suppress metastasis in colorectal cancer." (PMID 33836753, 2021). "In the present study, we investigated CD147 and MMP-11 expression in colorectal cancer." (PMID 26507719, 2015). "Similarly, there was also a significantly higher expression of MMP-11 in colorectal cancer tissue than in normal mucosa (77.06 vs. 33.94 %, P < 0.001)." (PMID 26507719, 2015). "This study implied that MMP11, MMP14, MMP17, and MMP19 are potential targets of precision therapy for patients with colorectal cancer." (PMID 34804973, 2021). "In gastric and colorectal cancers, the prevalence of MMP11+ mCAFs increased with tumor progression, although stage‐specific differences in colorectal cancer were not statistically significant." (PMID 40552583, 2025). "Furthermore, our analysis showed that high expression of MMP11 and MYL9 in human colorectal cancer was inversely correlated with TMB." (PMID 41009818, 2025). "Also, hsa-let-7c inhibits metastasis in colorectal cancer, and its downregulation stimulates the expression of K-RAS, MMP11, and PBX3 and promotes cell migration, glioblastoma, and invasion." (PMID 35490305, 2022). "Also, MMP11, MMP14, MMP17, and MMP19 are potential targets of precision therapy for patients with colorectal cancer." (PMID 34804973, 2021). "In this study we found that there was an increased expression of CD147 and MMP-11 in colorectal cancer compared with paired normal mucosa, suggesting that CD147 and MMP-11 might play an oncogenic role in colorectal cancer." (PMID 26507719, 2015).
lung carcinoma (15 papers, 2003 to 2025). "Furthermore, it is yet unknown whether MMP11 is related to immune escape in lung cancer, particularly in individuals with EGFR mutation-positive LUAD." (PMID 36756152, 2023). "MMP11 is expressed in many tumors, such as oral cancer, lung cancer, esophageal cancer, pancreatic cancer, invasive meningioma, ovarian cancer, and colon cancer, while expression in normal tissues is rare." (PMID 36756152, 2023). "Strong positive expression of MMP11 was significantly and negatively related to overall survival in a proteogenomic landscape investigation of lung cancer patients in East Asia." (PMID 36756152, 2023). "MMP11 expression was higher in lung cancer tissue than in normal tissue (normal, n = 59, yellow), regardless of EGFR mutation status, according to a comparison of 512 LUAD samples with identifiable EGFR mutations information in the TCGA database and 59 normal lung tissue samples." (PMID 36756152, 2023). "MMP-11 is abundantly produced in lung cancer interstitial fibroblasts." (PMID 33083004, 2020). "Strikingly, these cultures also express elevated Mmp10 mRNA, but no increase in Mmp2, Mmp7, Mmp9, Mmp11, Mmp12 or Mmp14, other Mmp species commonly linked to lung cancer." (PMID 22545096, 2012). "The role of MMP11 protease in lung cancer progression has been clearly defined." (PMID 18793406, 2008). "Overexpression of MMPs, in particular gelatinase A (MMP-2), gelatinase B (MMP-9) and stromelysin-3 (MMP-11), is related to tumour progression and metastasis in solid tumours including gastric, colon and lung cancer." (PMID 12771921, 2003). "MMP11 expression levels in lung cancer patients were non-significantly related to TNM stage, gender, race, age, or smoking (P > 0.05) but rather to their primary therapy outcome." (PMID 36756152, 2023). "Consequently, by downloading the RNAseq expression profiles of 57 pairs of matched lung cancer tissues from the TGCA database, we evaluated the variations in MMP11 expression between LUAD tissues and paraneoplastic tissues and conducted statistical descriptions." (PMID 36756152, 2023). "Some genes such as MMP11 (extra-cellular matrix proteins), XRCC1 (DNA repair), VEGF (regulator of angiogenesis), Cyclin D1 (cell cycle regulators) and tumor-suppressor genes (Semaphorin 3B, WNT-5A) have been found as down-regulated genes during lung cancer progression." (PMID 29593668, 2018). "We obtained five key genes such as GREM1, MMP11, SPP1, FOSB, and IL33 which were strongly associated with lung cancer in nonsmoking women, which improved understanding and could serve as new therapeutic targets, but their functionality needs further experimental verification." (PMID 34671675, 2021).
lymph node metastasis (14 papers, 2011 to 2025). "Specifically, MMP-11 has been linked to lymph node metastasis and increased malignancy, with high MMP-11 expression correlating with significantly reduced survival rates in oral cancer patients." (PMID 40282437, 2025). "In OSCC, the expression of MMP-11 is associated with an increased lymph node metastasis and a low survival rate." (PMID 36275775, 2022). "They observed that patients heterozygous or homozygous for the C allele of MMP-11 (rs738792) polymorphism presented with an increased incidence of lymph node metastasis in comparison to patients homozygous for T allele." (PMID 33681393, 2021). "Patients with strong MMP-11 expression, however, were associated with higher incidence of lymph node metastasis (p=0.034) and worse grade of tumor differentiation (p=0.009)." (PMID 28427180, 2017). "We found that MMP-11 expression was present in 118/279 (42.3%) cases and expression of MMP-11 was associated with higher incidence of lymph node metastasis and worse grade of tumor differentiation." (PMID 28427180, 2017). "Our data showed that a strong expression of MMP-11 was associated with increased lymph node metastasis and poor survival in these patients." (PMID 28427180, 2017). "In summary, by using immunohistochemical analysis, we observed that strong expression of MMP-11 in OSCC tissues was associated with an increased incidence of lymph node metastasis." (PMID 28427180, 2017). "However, in contrast, it was suggested that the MMP11 rs738792 C allele was associated with higher risk to develop to Child-Pugh B or C grade in HCC patients, and the C allele of MMP11 rs738792 was also suggested to be associated with increased incidence of lymph node metastasis in OSCC patients." (PMID 31940762, 2020). "The histopathological classification, Lauren classification, lymph node metastasis, CD8 T lymphocyte and CD163 macrophage infiltrations, and MMP-11 expression were significantly associated with the textural features of AGC." (PMID 36010928, 2022). "Serum levels of MMP11 were previously shown to be significantly higher in patients with lymph node metastasis and was also identified as an independent prognostic factor for 5-year mortality in CRC." (PMID 33648461, 2021). "Expression of CD147 and MMP-11 were both correlated with CRC lymph node metastasis (P = 0.021 and P = 0.031, respectively), distant metastasis (P < 0.001 and P = 0.013, respectively) and TNM stage (P = 0.006 and P = 0.049, respectively)." (PMID 26507719, 2015). "Since we found that expression of MMP-11 was significantly correlated with the presence of lymph node metastasis, the effects of the MMP-11 knockdown on the oral cancer cell line were investigated by cell migration assay." (PMID 25423087, 2014). "In conclusion, our study indicated that a substantial increase in the plasma level of MMP-11 by performing ELISA assay is useful for assessment of the disease progression, especially lymph node metastasis, in patients with OSCC." (PMID 25423087, 2014). "Our results showed that the plasma MMP-11 levels were significantly higher in patients with advanced T status (p = 0.001), lymph node metastasis (p = 0.006) and higher TNM stages (p<0.001)." (PMID 25423087, 2014). "In this study, MMP-11 protein levels appeared to correlate with invasion potential and high levels were related to the extent of lymph node metastasis in GC (P = 0.006), similar to data reported for other malignancies." (PMID 21513571, 2011). "Since we found that expression of MMP-11 was significantly correlated with the presence of lymph node metastasis, the effects of the MMP-11-overexpression on the OSCC cell line were investigated by in vitro wound-closure assay, Boyden chamber cell invasion and migration assay." (PMID 28427180, 2017). "Our study showed that plasma level of MMP-11 may be useful for assessment of the disease progression, especially lymph node metastasis, in patients with OSCC." (PMID 25423087, 2014).
lymph node metastasis (continued). "However, MMP-11 protein levels were significantly higher in patients suffering with advanced T status (T3+T4; p = 0.001), lymph node metastasis (N1+N2+N3; p = 0.006) and higher TNM stages (stage III + stage IV; p<0.001)." (PMID 25423087, 2014). "Serum MMP-11 levels were correlated with lymph node metastasis (P = 0.006)." (PMID 21513571, 2011). "However, MMP-11 protein levels were significantly higher in patients suffering with lymph node metastasis, including 31 local and 4 distant lymph node metastases, compared with peritoneal seeding and internal organ metastasis (P = 0.002 and P = 0.029, respectively)." (PMID 21513571, 2011). "However, MMP-11 could have a role in lymph node metastasis and could potentially be an independent factor for prognosis." (PMID 21513571, 2011). "In conclusion, our results revealed that the MMP-11 expression in OSCC samples can predict the progression, especially lymph node metastasis, and the survival of OSCC patients in Taiwan." (PMID 28427180, 2017). "Overexpression of MMP-11 correlates with patients having poorly differentiated tumors, lymph node metastasis and lacking progesterone receptor." (PMID 24564996, 2014).
ovarian carcinoma (14 papers, 2010 to 2025). A malignant neoplasm originating from the surface ovarian epithelium. "The presence of MMP-7, MMP-26, MMP-3, MMP-10, and MMP-11 expression has been previously confirmed in biopsy material from ovarian cancer patients." (PMID 41007705, 2025). "We also found one work that describes the diagnostic utility values for MMP-11 and MMP-26 in patients with ovarian cancer." (PMID 41007705, 2025). "This work is similar to the current study in which MMP-11 level is high in ovarian cancer patients as compare to healthy controls." (PMID 27902750, 2016). "MMP-11 in ovarian cancer patients were found elevated (63.58±8.48 ng/ml), vs control subjects (45.60±9.67 ng/ml)." (PMID 27902750, 2016). "The purpose of the present study was to determine the diagnostic utility of selected MMPs, MMP-2, MMP-3, MMP-11 and MMP-26, as new biomarkers in patients with ovarian cancer and to compare the results obtained with routinely determined markers CA125 and HE4 and the ROMA algorithm." (PMID 38892452, 2024). "MMP11 was found to be related with bowel metastases in ovarian cancer." (PMID 33282553, 2020). "MMP-11 expression correlates with ovarian carcinoma malignancy." (PMID 30792527, 2019). "MMP-11 is frequently found in ovarian carcinomas and is involved in ovarian cancer invasion." (PMID 27028996, 2016). "The MMP-11 expression is observed in the area that surrounds malignant epithelial tumour cells and sometimes in tumour cells of oesophageal, oral, papillary thyroid, colorectal, skin and ovarian carcinomas." (PMID 20160732, 2010). "Indeed, MMP-11 (or stromelysin-3) expression is more frequently observed in malignant ovarian carcinomas than tumors with low malignant potential." (PMID 20649989, 2010). "In conclusion, we are the first team to study the significance of MMP-2, MMP-3, MMP-11 and MMP-26 as new markers of ovarian cancer in comparison not only to HE4 and CA125, but also to the ROMA algorithm." (PMID 38892452, 2024). "Molecules such as VEGFA, MMP11 and TGF -β1 in particular CXCR2 play a very important role on cancer progression including ovarian cancer progression and hence their expressions with or without siRNA after anesthetic exposure were further determined." (PMID 27028996, 2016). "Stress variables (MDA, AGEs, AOPPs, NO), profile of antioxidants (SOD, Catalase, Vitamin E & A, GSH, GRx, GPx) and inflammatory biomarkers (MMP-9, MMP-2, MMP-11, IL-1α and TNF-α) were biochemically assessed from venous blood of fifty ovarian cancer patients and twenty healthy control subjects." (PMID 27902750, 2016). "MMP-2, MMP-3, MMP-11 and MMP-26 have not shown potential as stand-alone biochemical markers in ovarian cancer diagnosis." (PMID 38892452, 2024).